C1orf167 (chromosome 1 open reading frame 167)
Synonyms: DKFZp434E1410; RP11-56N19.2
Tractability: No criterion of Open Targets' tractability assessment is met for any kind of drug.
Gene: Protein-coding gene on chromosome 1 (11,761,787 to 11,789,585, forward strand). Ensembl gene ENSG00000215910.
Genetic constraint (gnomAD): Loss-of-function variants: 123 observed, 131.37 expected, observed/expected ratio (o/e) 0.94, 90% interval 0.81 to 1.09. The synonymous counts are far from expectation, so gnomAD's model fits this gene poorly and the ratio says little. Missense variants: 1,272 observed, 1,459.3 expected, observed/expected ratio (o/e) 0.87, 90% interval 0.83 to 0.91. Synonymous variants: 513 observed, 614.3 expected, observed/expected ratio (o/e) 0.84, 90% interval 0.78 to 0.9.
Homologues: Orthologues: chimpanzee C1H1orf167 (83% identical), macaque C1H1orf167 (72% identical), dog C2H1orf167 (39% identical).
Diseases named in the same sentence as C1orf167 in open-access papers:
C1orf167 is named in the same sentence as 2 diseases in open-access papers, as found by Europe PMC text mining. Sharing a sentence is not in itself a finding about the gene and the disease. The quoted sentences say what the papers report.
cancer (1 paper, 2024). A tumor composed of atypical neoplastic, often pleomorphic cells that invade other tissues. "In addition, we also identified 6 upregulated genes not typically associated with cancer (ARC, C1orf167, CNGA3, KRT75, SPRR1B, STUM)." (PMID 38038766, 2024).
C1orf167 also shares sentences with these, for which no sentence is quoted: cardiovascular disease (1 paper).